LEP (leptin)
Diseases named in the same sentence as LEP in open-access papers (continued):
Sharing a sentence is not in itself a finding about the gene and the disease.
Obesity (continued). "Overweight/obesity may also elicit disturbances in bioactive compounds, such as lipids, leptin function and adipokines." (PMID 37842297, 2023). "In a previous study we reported that increased leptin level was related to obesity regardless of associated diabetes while elevated level of tumor necrosis factor-α was linked to obesity that is associated with diabetes." (PMID 36950695, 2023). "Interestingly, leptin (LEP), a hormone involved in seasonal food-seeking behavior, thermoregulation, and obesity, was regulated only in winter in three tissues: adipose visceral, nerve, and blood." (PMID 36745672, 2023). "Total ghrelin levels are suppressed in non-PWS children and adults with exogenous obesity or with obesity caused by mutations in leptin or the melanocortin-4 receptor." (PMID 37175718, 2023). "Moreover, obesity can contribute to the exacerbation of inflammation in severe persistent allergic rhinitis through increased IL-1β and leptin levels." (PMID 37686715, 2023). "However, leptin prevents obesity by promoting satiety, reducing hunger, and increasing insulin sensitivity." (PMID 37363537, 2023). "Furthermore, leptin is involved in the regulation of signal pathways related to obesity, for example, inflammation and endoplasmic reticulum stress." (PMID 38089630, 2023). "As a cytokine-like hormone, leptin serves as a bridge between BC and obesity." (PMID 36880535, 2023). "Central and peripheral leptin resistance may be present under pathophysiological conditions such as hyperlipidemia, hypertension, atherosclerosis, obesity, inflammation, and IR of the MetS." (PMID 36984562, 2023). "Obesity is correlated with an increase in BMAds in mice and humans, which are known contributors to systemic adipokines such as leptin (pro-myeloma) and adiponectin (anti-myeloma), however the relationship between MM and BMAds has only begun to be investigated." (PMID 36909335, 2023). "Leptin levels also displayed the same pattern as hsCRP showing increased levels with obesity." (PMID 38189043, 2023). "In terms of HM and obesity prevention, the knowledge of the HM macronutrient composition, specifically protein concentrations, is essential; however, the levels of the regulatory adipose tissue hormones leptin and adiponectin are also crucial." (PMID 36678304, 2023). "Obesity in humans occurs as the result of an imbalance between energy intake and expenditure, possibly as a consequence of impaired leptin signaling in the presence of elevated circulating leptin levels." (PMID 37217565, 2023). "However, clinical studies indicate that leptin is undesirable as a therapeutic regiment for obesity, which is at least partly attributed to the poorly understood complex secondary structure and key signaling mechanism of the leptin-responsive neural circuit." (PMID 37043384, 2023). "The IN delivery of the obesity-related hormone leptin has also been extensively addressed." (PMID 37371113, 2023). "In conclusion, analysis suggests that weight loss with or without exercise is effective for decreasing leptin levels and increasing the A:L ratio in breast cancer survivors with overweight or obesity." (PMID 37571390, 2023). "It has been well reported that SFN could reduce obesity through many mechanisms, such as reversing leptin resistance, browning the white fat, and promoting lipolysis." (PMID 37513640, 2023). "Leptin signaling within the ventral tegmental area (VTA) plays a crucial role in the regulation of energy homeostasis, and its dysfunction has been implicated in obesity and metabolic disorders." (PMID 38027481, 2023). "This study demonstrated that weight loss induced by RYGB in patients with severe obesity with or without MetS improved biochemical and systemic inflammatory parameters, particularly the adiponectin/leptin ratio." (PMID 37571250, 2023).
Obesity (continued). "Obesity is related to an increase in leptin levels and a decrease in adiponectin concentrations, which alters miRNAs expressions, including let-7, miR-27, and miR-143, that are involved in both obesity and cancer." (PMID 36674935, 2023). "In addition, leptin resistance in Nln-/- and WT animals fed HD under the present diet-induced obesity model, with sweetened condensed milk and multivitamin complex addition, also need to be investigated." (PMID 37894869, 2023). "This information is consistent with findings from more recent studies in which LAR values could be a more efficient predictor of obesity-related complications compared to leptin or adiponectin levels." (PMID 36967781, 2023). "In addition to their effects on insulin and leptin, polyphenols have been shown to exert anti-obesity by directly modulating neuropeptides in food intake, as anthocyanins were reported to inhibit neuropeptide Y, suppressing obesity in high-fat diet-fed rats." (PMID 36829976, 2023). "Leptin concentrations are positively correlated with obesity." (PMID 37048738, 2023). "In addition, leptin resistance and increased leptin levels are frequently observed in individuals with obesity." (PMID 37763777, 2023). "Obesity is associated with chronic low-grade inflammation in adipose tissue, which can lead to the release of cytokines and adipokines, such as TNF-alpha and leptin, which contribute to the development of insulin resistance." (PMID 37240215, 2023). "TNF-α secretion in obesity is increased by leptin and resistin levels." (PMID 37371961, 2023). "Owing to these observations, we speculate that decreased leptin action may attenuate metabolic action of HJGE in HFD-induced obesity." (PMID 37251332, 2023). "Our results also suggest hyperinsulinemia may promote leptin resistance, leading to development of obesity and hyperphagia later in childhood." (PMID 37546289, 2023). "However, when leptin levels are abnormal (too high or too low) for a number of reasons, it can negatively affect your health, inducing inflammatory responses, obesity, and other problems." (PMID 37986371, 2023). "Moreover, our group and others demonstrated a central role of CK2 in AT, obesity and adipogenesis, and we provided additional insights on the role of leptin, which results in increased peritumoral AT, in cancer progression and chemo-resistance." (PMID 37238992, 2023). "Moreover, obesity increases the expression of caveolin-1, a major component of the caveolae (small membrane invaginations), which attenuates leptin-dependent adiponectin secretion." (PMID 36520252, 2023). "Secreted by adipose tissue, leptin prevents obesity and has a neuroprotective function as well." (PMID 37363537, 2023). "In this regard, understanding the pathogenesis of overweight-related and obesity-related disorders, and the control of energy homeostasis by leptin may provide new alternatives for overweight/obesity treatment." (PMID 37240998, 2023). "In turn, obesity leads to vagal dysfunction, which specifically hampers leptin response." (PMID 37238993, 2023). "It is also suggested that increased irisin in obesity may be to overcome insulin and irisin resistance, similar to well-documented leptin resistance in obesity." (PMID 38333723, 2023). "High serum leptin levels may be a possible mechanism for the profitable effects of obesity on cognitive function in old age." (PMID 37927863, 2023). "Ob/ob mice are an obese model carrying a genetic mutation in the Leptin gene, which does not fully represent the models of obesity." (PMID 37860765, 2023). "After discovering leptin in 1994, it was hypothesized that increased leptin concentrations should have led to decreased appetite and increased energy expenditure in obesity." (PMID 38068822, 2023). "Leptin resistance further develops disruptions in the signaling pathways and obesity." (PMID 37363537, 2023). "Notably, the observed massive obesity in the Kir2.1-injected mice was refractory to icv leptin treatment." (PMID 37069175, 2023).
Obesity (continued). "In this study, we set out to understand whether the leptin signal to T cells in obesity is sufficient to drive systemic inflammation and metabolic disease." (PMID 37276236, 2023). "Furthermore, leptin plays a crucial role in the development of low-grade systemic inflammation in obesity." (PMID 38260160, 2023). "In both cohorts, leptin was increased with similar serum levels as well as diagnostic performance (AUROC >0.80), suggesting that serum leptin can identify NAFLD without obesity." (PMID 37753211, 2023). "Moreover, because leptin and adiponectin have opposing effects in cells, the balance between those two adipokines is essential and the changes in their ratio link obesity and cancer." (PMID 37444627, 2023). "In the present study, we aimed to investigate the ability of obesity-related concentrations of leptin to modulate the in vitro effector and regulatory Fel d1-specific CD4+ T-cell subsets in patients allergic to cat, considered the third most common cause of respiratory allergy in humans." (PMID 37954580, 2023). "Leptin resistance has been well documented to drive obesity progression." (PMID 36512408, 2023). "Among the adipokines related to obesity, leptin is related to the inflammatory response." (PMID 37488474, 2023). "Moreover, leptin is known to promote a pro-inflammatory immune response, and it is suggested to be an important factor linking obesity, MS, and cardiovascular diseases." (PMID 37960185, 2023). "Stage I obesity participants had significantly higher levels of plasmatic leptin (p < 0.001) and serum glucose (p = 0.001) and lower levels of plasmatic ghrelin (p < 0.001) with regard to LS and lower levels of plasmatic ghrelin (p < 0.001) with respect to OW participants." (PMID 36904115, 2023). "We propose FGF21 as a marker able to differentiate metabolic health in children with normal weight, while leptin could be used to detect unfavorable metabolic profiles under states of already established obesity." (PMID 38138907, 2023). "Consistent with this, results from a longitudinal study in humans that evaluated changes in endocrine factors (i.e., ghrelin, insulin, and leptin) in obesity assessed before and after bariatric surgery, reported a decrease in ghrelin, insulin, and leptin after the intervention." (PMID 37261609, 2023). "Leptin was, thus, initially known as the “anti-obesity” hormone." (PMID 37892180, 2023). "Intriguingly, LPS, like obesity, has been shown to cause leptin resistance via induction of the negative cellular regulator, PTP-1B." (PMID 36769012, 2023). "However, its effect is barely detectable in people with hyperleptinemia (type 2 obesity), limiting the utility of leptin as an anti-obesity drug." (PMID 37547309, 2023). "Thus, despite high circulating levels of leptin, people with obesity have a decreased sensation of satiety, promoting overweight and obesity." (PMID 37508717, 2023). "Other mutations within the leptin–melanocortin pathway, such as in proopiomelanocortin (POMC), melanocortin receptor 4 (MC4R), brain-derived neurotrophic factor (BDNF), and the tyrosine kinase receptor B (NTRK2) genes, can also contribute to obesity." (PMID 37762850, 2023). "It has been proven that leptin concentrations are significantly increased in obesity." (PMID 37960185, 2023). "Moreover, a number of studies have demonstrated that supplementation with probiotic and prebiotic foods improves glucose parameters and leptin concentrations in patients with obesity, diabetes, and nonalcoholic fatty liver disease." (PMID 37238961, 2023). "Blood leptin levels are positively correlated with obesity and weight gain." (PMID 37691744, 2023). "Leptin level was higher in obese than that in the normal weight cases, which means that obesity may be a leptin resistance condition." (PMID 36914629, 2023). "Leptin is central to the obesity-cancer link since it is produced in proportion to fat mass." (PMID 37361533, 2023).
Obesity (continued). "Potential mechanisms may be that obesity affects the liver through adipokines (e.g., leptin and adiponectin), hormones derived from adipose tissue." (PMID 36991386, 2023). "It is hypothesized that leptin and/or other systemic adipokines could contribute to the endothelial activation and dysfunction observed in severe COVID-19 patients with obesity." (PMID 36509969, 2023). "Leptin resistance has been suggested to be a major culprit for obesity development." (PMID 37069175, 2023). "Obesity can lead to leptin resistance and subsequent high leptin concentrations." (PMID 37033164, 2023). "Future studies should examine whether the effects we describe here for Cmpd 1 in the ZSF1 model setting translate to non-leptin models of obesity and whether they can be reasonably expected to extend to humans, in particular those afflicted by T2D." (PMID 37805649, 2023). "The close values for the explanation of leptin by the healthy and traditional patterns may be due to the high prevalence of overweight and obesity in this population." (PMID 37231745, 2023). "Obesity leads to leptin resistance and alters its normal functions." (PMID 37629396, 2023). "Therefore, excessive SOCS3 activity is considered as a potential mechanism for the leptin resistance that characterizes human obesity." (PMID 36978976, 2023). "Indeed, while short-term leptin treatment leads to the activation of MSC, the consequence of long-term exposure to leptin, which occurs during obesity has been under-investigated." (PMID 36750692, 2023). "Leptin, upregulated in obesity, affects blood pressure through sympathetic activation, and leptin resistance might contribute to hypertension." (PMID 37987283, 2023). "Obesity engenders a low-grade inflammatory state, which may also depend, in part, on increased leptin levels." (PMID 36769012, 2023). "Leptin provokes an inflammatory phenotype, suggesting that an increased level of leptin in obesity could increase the chances of pulmonary inflammation in COVID-19 infection." (PMID 37013538, 2023). "Hyperleptinemia and leptin resistance are closely related to obesity and T2DM." (PMID 37371675, 2023). "Weight loss, with or without exercise, was associated with decreased leptin levels in breast cancer survivors with overweight or obesity." (PMID 37571390, 2023). "A previous study demonstrated transient increases in serum leptin levels from the neonatal to prepubertal period and also showed that maternal food restriction during pregnancy disturbed the leptin surge, resulting in leptin resistance and obesity in adulthood." (PMID 37375670, 2023). "The mechanism by which obesity interacts with genetic factors is beyond the scope of this work, but obesity has been suggested to be neuroprotective due to hormonal changes (e.g., leptin, estrogen), dietary factors (e.g., vitamin E and D levels), and less risk for fragility." (PMID 37731955, 2023). "Obesity may induce adipose tissue to release more leptin and less adiponectin, and researchers have demonstrated that this can enhance the activity of osteoclasts and cause bone loss." (PMID 38075068, 2023). "Combining leptin treatment with leptin sensitizers may thus help overcome leptin resistance and, also obesity, as a result." (PMID 36790719, 2023). "Medium and high doses of 1,3C‐2D‐TAG structured lipids could significantly reduce diet‐induced leptin concentrations in the mice and could effectively alleviate obesity‐induced leptin resistance." (PMID 37576038, 2023). "As a result, leptin-mediated sympathetic activation carried in the circulatory system and at the renal stage could potentially impact BP management and lead to obesity-related hypertension." (PMID 35334523, 2022). "In addition to adipokines such as leptin, M1-type macrophages recruited by hypertrophy or dysfunctional adipose tissues in obesity further secrete proinflammatory cytokines including TNFα and IL-6, which can regulate hepcidin expression." (PMID 36335331, 2022).
Obesity (continued). "Leptin is a product of the obese gene that is mainly secreted by adipocytes, and its levels in the white adipose tissue and plasma are related to the energy storage so that leptin increases in obesity and decreases during fasting." (PMID 35154693, 2022). "Leptin is a protein synthesized in the fatty tissues and is effective for the control of obesity." (PMID 35386254, 2022). "Obesity was induced by the consumption of a high fat, high sucrose diet, the altered glucose homeostasis was measured by a glucose tolerance test, and the sex hormone, cytokine and adipokine levels (kisspeptin, leptin, adiponectin) were also measured." (PMID 35743826, 2022). "Obesity is accompanied by a series of metabolic alterations, and different metabolic cytokines and hormones, such as leptin, ghrelin, insulin, as well as certain central lipids may impact the HPG axis, and participate in the fine-tuning of puberty." (PMID 36465655, 2022). "Morbid obesity, defined as BMI equal to or greater than 40, is associated with hyperleptinemia and increased leptin impairs the negative feedback mechanism between the adipose tissue and neurons in the hypothalamus." (PMID 36010901, 2022). "Leptin resistance is found in many overweight patients and exacerbates their obesity." (PMID 36698957, 2022). "In addition, Hazzouri and colleagues found that obesity interferes with the neuroprotective effect of leptin on the brain leading to leptin resistance." (PMID 35739488, 2022). "Markers of inflammation such as interleukin-1 beta (IL-1β), tumor necrosis alpha (TNF-α), monocyte chemoattractant protein-1 (MCP-1 or CCl-2), and interleukin 6 (IL-6), and markers related to obesity such as leptin and insulin were measured systemically in the blood." (PMID 36387539, 2022). "In contrast, alcohol intoxication in leptin-deficient obese mice increased CYP2E1 activity only in liver microsomes but not in mitochondria, thus suggesting that leptin deficiency and/or obesity might hamper mitochondrial targeting of induced CYP2E1." (PMID 35053404, 2022). "Consequently, the adiponectin/leptin ratio has been proposed as a predictive marker for adipose tissue dysfunction in obesity and cardiometabolic syndrome." (PMID 36232660, 2022). "Anorexia and obesity are disorders of energy metabolism known to be altered by leptin dysfunction." (PMID 35886710, 2022). "Inspired by the idea to trigger the immune response to endogenous oversecreted leptin for obesity control, we proposed in the current study to develop an oral yeast vaccine for leptin knock-down based on our previous studies and came up with a novel concept in vivo protein interference (iPRTi)." (PMID 35774455, 2022). "Moreover, deceased patients with obesity as one of the comorbidities presented upregulation of genes in the leptin pathway in lung tissue samples." (PMID 35837843, 2022). "Obesity is central to development of MetDys, which originates with obesity-induced adipose tissue dysfunction, resulting in altered serum levels of adipocytes leptin and adiponectin and induction of chronic systemic inflammation." (PMID 35936059, 2022). "In obesity, women develop leptin resistance leading to cycle disorders." (PMID 35239212, 2022). "Therefore, the increased leptin levels observed in the high fat diet group, further confirm the state of obesity." (PMID 36451148, 2022). "Antipsychotic-induced weight gain/obesity is also associated with several neuropeptides or hormones that regulate energy balance and neuroendocrine function such as proopiomelanocortin (POMC), NPY, AgRP, insulin, leptin, and ghrelin." (PMID 36188456, 2022). "Leptin has been found to be a powerful chemoattractant of monocytes/macrophages and a promoter of their migration, which plays an important role in the development of obesity and concomitant diseases." (PMID 36499312, 2022).